RN7SL83P (RNA, 7SL, cytoplasmic 83, pseudogene)
Gene: Miscellaneous RNA gene on chromosome 7 (38,531,042 to 38,531,338, reverse strand). Ensembl gene ENSG00000241756.
Homologues: Orthologues: chimpanzee Metazoa_SRP (98% identical), macaque Metazoa_SRP (82% identical), rabbit Metazoa_SRP (64% identical). Paralogues in human: RN7SL1 (85% identical), RN7SL2 (84% identical), RN7SL3 (83% identical), RN7SL333P (82% identical), RN7SL126P (80% identical), RN7SL278P (80% identical), RN7SL113P (80% identical), RN7SL220P (80% identical), RN7SL509P (80% identical), RN7SL344P (80% identical), RN7SL559P (80% identical), RN7SL732P (80% identical), and 705 more.